IL11 (interleukin 11)
Diseases named in the same sentence as IL11 in open-access papers (continued):
Sharing a sentence is not in itself a finding about the gene and the disease.
diabetes (5 papers, 2017 to 2024). "Overall, this investigation illuminates the discovery of common molecular mechanisms underlying kidney stones and diabetes, unveils potential diagnostic biomarkers, and elucidates the significance of IL11 in these conditions." (PMID 37480086, 2023). "Moreover, elucidating the underlying roles of IL11 in kidney stones with diabetes necessitates additional investigations." (PMID 37480086, 2023). "The results of this study demonstrated that induction of diabetes significantly decreased pulmonary levels of IL-10 and IL-11 in the Dia group compared to the Col group (P<0.01)." (PMID 38164478, 2024). "Diabetes reduced the IL-10, IL-11, and Nrf2 levels (P<0.001 to P<0.01) and increased the levels of TNF-α and NF-κB compared to the Col group (P<0.001)." (PMID 38164478, 2024). "Our results indicated a marked elevation in the levels of IL11 expression in both kidney stones group and diabetes group when contrasted with the control cohort." (PMID 37480086, 2023). "Nonetheless, in the last decade, curiosity in IL-11 has flourished once again due to its involvement in numerous illnesses including diabetes and various kidney diseases." (PMID 37480086, 2023). "Upon comparison of the results from these algorithms, a single potential biomarker, IL11, was identified as a shared biomarker for both kidney stones and diabetes." (PMID 37480086, 2023). "Further investigation revealed that PROM1, TFPI2, and PFKFB3 are crucial genes involved in the regulation of IL11 expression in patients with kidney stones and diabetes." (PMID 37480086, 2023). "Expression analysis of IL11 demonstrated elevated levels in kidney stones and diabetes groups compared to controls." (PMID 37480086, 2023). "This investigation sought to expand on the significance of IL11 in the onset of nephrolithiasis among individuals afflicted with diabetes." (PMID 37480086, 2023). "This interaction implies that resveratrol holds promise as a therapeutic remedy for the management of diabetes and kidney stone conditions by targeting IL11." (PMID 37480086, 2023). "These authors have also demonstrated the protective effect of IL-11, in preventing multiple low doses of streptozotocin diabetes through enhancement of anti-inflammatory responses in islets." (PMID 29317893, 2017). "The present findings showed that voluntary exercise could have therapeutic effects on diabetes mellitus type 2, and it improved its pulmonary complication by elevation of the levels of Nrf2, IL-10, and IL-11 as well as decreasing TNF-α and NF-kB levels." (PMID 38164478, 2024). "As revealed in the present study, diabetes induction diminished IL-11 in lung tissue, and exercise could increase its pulmonary level." (PMID 38164478, 2024). "In this regard, the study aimed to investigate the role of the IL-6 cytokine family (sIL-6Ra, gp130/sIL-6Rb, and IL-11) in the regulation of mitochondrial dynamics in the liver in obese patients and to assess the contribution of these cytokines to the pathogenesis of type 2 diabetes mellitus (T2DM)." (PMID 33579000, 2021). "The association of Metrnl with hs‐CRP (r = −0.141; P = 0.009), IL‐1β (r = −0.240; P = 0.002), and IL‐11 (r = 0.178; P = 0.025) remained statistically significant even after adjustments for age, sex, smoking, alcohol intake, diabetes, BMI, Cr, FBG, TC, TG, and LDL‐C." (PMID 30394666, 2019). "Analysis of the Woroniecka Diabetes in Nephroseq v5 database showed a significant negative correlation between IL11 expression and the value of GFR." (PMID 37480086, 2023). "Despite the absence of another appropriate database to validate IL11 expression levels in kidney stones, our findings were confirmed by analysis of the GSE38642 dataset of diabetes patients." (PMID 37480086, 2023).
glioma (5 papers, 2019 to 2025). A benign or malignant brain and spinal cord tumor that arises from glial cells (astrocytes, oligodendrocytes, ependymal cells). "Accordingly, in mouse glioma tissue, IL11 level was inhibited in both the ITE and the ITE+PD1 group, with the ITE+PD1 group reaching statistical significance." (PMID 40283908, 2025). "The IGLoS signature consists of six immune infiltration‐related genes associated with the survival of diffuse patients with glioma, which are CCL19, ICOSLG, IL11, PTGES, TNFAIP3, and TRAF3IP3." (PMID 40714831, 2025). "As expected, ITE treatment reduced IL6/IL11 in cultured glioma cells." (PMID 40283908, 2025). "Next, we used the LASSO regression to further select six key regulators consisting of CCL19, ICOSLG, IL11, PTGES, TNFAIP3, and TRAF3IP3, and they were named the Immune Glioma Survival Signature (IGLoS signature)." (PMID 40714831, 2025). "Our discovery of the opposite regulation of IL11 by ITE and kynurenine suggests that it is an AHR target in glioma." (PMID 40283908, 2025). "In the Gusu in‐house dataset consisting of 24 patients with glioma, TRAF3IP3, TNFAIP3, ICOSLG, IL11, and PTGES, showed a trend of increasing expression with increasing tumor grade, whereas CCL19 was not." (PMID 40714831, 2025). "Interestingly, glioma tissue displayed an increase in pSTAT3 levels upon ITE+PD1 treatment, suggesting that IL-11 and IL-6 are likely not the primary regulators of STAT3 in this context and highlighting STAT3 as a potential target for combination therapy." (PMID 40283908, 2025).
ischemic stroke (5 papers, 2017 to 2024). A stroke disorder caused by obstruction of blood flow to the brain, due to thrombotic (local blood clot formation) or embolic (due to a blood clot or other material traveling from another site) event. "We draw ROC curves to assess the diagnostic value of IL-11 for poor prognosis of ischemic stroke patients." (PMID 36875689, 2023). "The result showed that IL-11 could be a potential diagnostic biomarker of poor prognosis of ischemic stroke patients, the AUC of IL-11 was 0.965, cutoff value was 87.31 pg/mL, sensitivity was 87.5%, and specificity was 87.2%." (PMID 36875689, 2023). "IL-11 could be a potential diagnostic biomarker of poor prognosis of ischemic stroke patients." (PMID 36875689, 2023). "Our findings are consistent with previous studies, describing pericyte production of IL6 as early as 2 h after hypoxic treatment and Il11 expression 24 h after ischemic stroke." (PMID 37378751, 2024). "IL6 has been described to have a bidirectional role in ischemic stroke, being both harmful and protective, while IL11 seem to have a protective role after ischemic stroke, despite having controversial roles in other processes such as fibrosis and inflammation." (PMID 37378751, 2024). "This study demonstrated that the ischemic stroke patients in the RT group had higher serum IL-11 levels and better prognosis." (PMID 36875689, 2023). "We aimed to explore the expression of IL-11 in ischemic stroke patients and its correlation with rehabilitation training and prognosis." (PMID 36875689, 2023). "In the present study, we also demonstrated for the first time in a clinical trial that IL-11 was progressively elevated in recovering of ischemic stroke patients and correlated with cytokines and prognosis of ischemic stroke patients." (PMID 36875689, 2023). "In this randomized control research, we aimed to explore the expression of IL-11 in ischemic stroke patients and its correlation with rehabilitation training and prognosis." (PMID 36875689, 2023). "It was found that IL-11 (95% CI 0.346~0.799, P = 0.03), NIHSS score, infarct volume, TG, HDLC, and IL-6 were the risk factors for bad prognosis of ischemic stroke patients." (PMID 36875689, 2023). "In our present research, we found that the serum levels of IL-11 were declined in ischemic stroke patients with bad prognosis." (PMID 36875689, 2023). "This study might reveal the clinical significance of IL-11 in ischemic stroke patients, as well as provide novel research targets for ischemic stroke treatment." (PMID 36875689, 2023). "Thirdly, the molecular mechanism of IL-11 affecting ischemic stroke development is unclear." (PMID 36875689, 2023). "However, the serum IL-11 levels of ischemic stroke patients were obviously decreased in the mRS score ≥ 3 group." (PMID 36875689, 2023). "Furthermore, IL-11, NIHSS score, and rehabilitation training were the risk factors for poor prognosis of ischemic stroke patients." (PMID 36875689, 2023). "In addition, the serum IL-11 levels of ischemic stroke patients were obviously decreased in the mRS score ≥ 3 group." (PMID 36875689, 2023). "In summary, the present study showed that the ischemic stroke patients in the RT group had higher serum IL-11 levels and better prognosis, indicating that rehabilitation training might improve the prognosis of ischemic stroke patients and elevate the levels of IL-11." (PMID 36875689, 2023). "Also, many genes encoding chemokines, cytokines and chemokine receptors, which are involved in neuroinflammatory processes in ischemic stroke, were regulated, including Cxcr2 in endothelial cells, Ccl5, Il11 and Il6 in pericytes, Lcn2 in astrocytes and pericytes, and Il1rn in microglia." (PMID 35752654, 2022). "The NIHSS score, the proportion receiving rehabilitation training, and the levels of IL-11, triglyceride (TG), and high-density leptin cholesterol (HDLC) of ischemic stroke patients in the mRS score ≥ 3 group were remarkably elevated than that in the mRS score ≤ 2 group." (PMID 36875689, 2023).
ischemic stroke (continued). "However, there is no clinical study on IL-11 in ischemic stroke patients." (PMID 36875689, 2023).
periodontal disease (5 papers, 2012 to 2023). "It has been reported that the twice-weekly administration of recombinant human IL-11 in periodontal disease model acted by blocking proinflammatory cytokines, leading to a reduction in attachment loss and bone resorption and improvement of the inflammatory reaction." (PMID 23226926, 2012). "Meanwhile, the decreased ratio of IL-11/IL-17 might reflect an imbalance between the proinflammatory and anti-inflammatory cytokines in different periodontal diseases." (PMID 23226926, 2012). "It was predicted that IL-11 may be considered as a candidate molecule for therapeutic modulation of the host response in the management of periodontal diseases." (PMID 23226926, 2012). "Most previous studies have focused on the analysis of ratios between pro-inflammatory and anti-inflammatory cytokines, or vice versa, in periodontal diseases, with IL1beta/IL10 and IL11/IL17 being the most evaluated." (PMID 30573746, 2018). "Hence, it may be that IL11 levels in the crevicular fluid should not be interpreted as inflammatory markers in periodontal diseases, but reflect the attempt of the tissue to repair." (PMID 37892923, 2023).
steatosis (5 papers, 2021 to 2025). Increased lipid within the cytoplasm of cells. "IL-11 can cause liver inflammation, steatosis, fibrosis and liver failure." (PMID 41333471, 2025). "IL-11 can promote the development of liver diseases, eventually leading to inflammation, steatosis, fibrosis and liver failure." (PMID 41333471, 2025). "In mice deleted for Il11ra1, restoration of IL11 cis-signaling in hepatocytes reconstitutes steatosis and inflammation but not fibrosis." (PMID 33397952, 2021).
bone cancer (4 papers, 2015 to 2023). A primary or metastatic malignant neoplasm affecting the bone or articular cartilage. "There were a number of reports that documented the involvement of IL-11 in various malignancies including gastric, colorectal, pancreatic, prostate, breast, ovarian, endometrial, and bone cancers, and some studies have been published on targeting IL-11 signaling in preclinical models of cancer." (PMID 34497605, 2021). "qRT-PCR analysis indicated that bone tumors from mice treated with 1 μg/day and 5 μg/day halofuginone expressed significantly lower mRNA levels of RANKL and IL-11 than control groups." (PMID 26015407, 2015).
coronary artery disease (4 papers, 2019 to 2023). "IL-11 levels were observed to increase in human coronary artery disease (CAD) and aortic dissection (AD)." (PMID 30728748, 2019). "An important TGFβ1-related signaling cascade is activated in cardiac fibroblasts from patients with coronary artery disease when compared with controls, and the inhibition of IL11, a main downstream target of TGFβ1, leads to reduced fibrosis in the heart using murine model." (PMID 32664951, 2020).
gingivitis (4 papers, 2012 to 2024). A disorder involving inflammation of the gums; may affect surrounding and supporting structures of the teeth. "IL-11 was analyzed in two case-control studies in patients with gingivitis using the ELISA technique." (PMID 24790719, 2014).
Hepatitis (4 papers, 2017 to 2024). Inflammation of the liver. "Results of this research demonstrated that bLf is able to improve the expression of interleukin 11 (IL-11) and bone morphogenetic protein 2 in the small intestine and to protect mice with hepatitis against inflammation." (PMID 32847014, 2020). "For IL-11, although effective, the drug-related adverse events rate is as high as 30-50%, including edema, fever, hepatitis, coagulopathy, fatigue, and arthralgia." (PMID 30174705, 2018). "The findings indicate that the up-modulation of IL-11 levels by bLf seems to provide therapeutic action in the small intestine induced by LPS-zymosan in this model of hepatitis." (PMID 28257033, 2017).
kidney damage (4 papers, 2021 to 2024). "In humans, elevated urinary IL-11 levels have been observed in patients with nephropathy and nephritis, and IL-11 ranks among the most up-regulated genes in tissue slices isolated from individuals with end-stage kidney disease." (PMID 37816442, 2023). "Canonical IL-11 and TGFβ1 signaling stimulate myofibroblasts for the transient production of ECM, supporting TECs in completing the repair and achieving physiological resolution of kidney damage." (PMID 38732588, 2024). "The levels of IL-11 increase.Inhibition of IL-18 can significantly prevent kidney damage.CCL5 and IL-1α slightly increase.Inhibition of TNF-α cannot significantly reduce kidney damage.NLRP3 pathway is the key pathogenesis of inflammation." (PMID 34149721, 2021). "The levels of IL-11 do not increase.Inhibition of IL-18 cannot significantly prevent kidney damage.CCL5 and IL-1α significantly increase.Inhibition of TNF-α can significantly reduce kidney damage.NLRP3 pathway is less important." (PMID 34149721, 2021).
leukemia (4 papers, 2008 to 2023). A malignant (clonal) hematologic disorder, involving hematopoietic stem cells and characterized by the presence of primitive or atypical myeloid or lymphoid cells in the bone marrow and the blood. "Chinese researchers examined the effects of IL-11 gargle and aerosol therapy on OM caused by leukemia chemotherapy and allogeneic hematopoietic stem cell transplantation." (PMID 37438702, 2023). "CNTF, which is a pluripotent neurotropic factor and is related with the cytokine family that includes IL-6, IL-11, leukemia inhibitory family, and oncostatin, binds and signals to maintain the bone homeostasis through the gp130 coreceptor subunit." (PMID 33833854, 2021). "IL-11 induces concentration-dependent proliferation when incubated with human TF-1 leukemia cells (; and data not shown)." (PMID 18941632, 2008).
Myocardial fibrosis (4 papers, 2019 to 2025). "Hence, it is likely that blockade of IL-11 (either in Il11-deficient mice or by IL-11–neutralizing antibodies), led to reduction in myocardial fibrosis and improvement of cardiac dysfunction through diminished ERK signaling and limited ECM production." (PMID 38093747, 2023). "Using protein assays, bulk RNA-sequencing, and in vivo imaging, we analyzed the effects of IL11 on myocardial fibrosis, inflammation, and cardiac function, challenging previous reports suggesting the cardioprotective potential of IL11." (PMID 37629170, 2023). "Growth factors and pro-inflammatory cytokines involved in myocardial fibrosis include connective tissue growth factor (CTGF), tissue growth factor-β (TGF-β), tumour necrosis factor-α (TNF-α), interleukin-11 (IL-11) and galectin-3 (Gal-3)." (PMID 40910148, 2025).
ovarian carcinoma (4 papers, 2019 to 2026). A malignant neoplasm originating from the surface ovarian epithelium. "Our results indicate that EGCG, I3C, and Pano significantly downregulate levels of the protumorigenic cytokine IL-11, which is a major factor implicated in the chemoresistance of ovarian cancer cells through the activation of the JAK2-STAT5 pathway." (PMID 37509102, 2023). "In platinum‐resistant ovarian cancer cells, IL‐11 expression is intensified." (PMID 40968783, 2026). "In platinum‐resistant ovarian cancer cells, elevated reactive oxygen species induce FOSL1 expression, which binds to the IL‐11 promoter and drives its autocrine upregulation." (PMID 40968783, 2026).
pneumonia (4 papers, 2019 to 2024). An acute, acute and chronic, or chronic inflammation focally or diffusely affecting the lung parenchyma, caused by an infection in one or both of the lungs (by bacteria, viruses, fungi, or mycoplasma.). "This suggests epithelial cells are a prominent source of IL-11 in both the absence and presence of pneumonia." (PMID 31415618, 2019). "Since IL-11 levels are maintained at relatively high levels at baseline, we utilized neutralizing antibodies to assess the roles of this cytokine during pneumonia." (PMID 31415618, 2019). "Given the important role other gp130-signaling cytokines play in pneumonia, along with IL-11’s established roles in other inflammatory settings, we sought to understand the role of IL-11 in pneumonia." (PMID 31415618, 2019). "Our previous work demonstrated a small increase in IL-11 mRNA in the lung during pneumonia, suggesting a possible role for this cytokine during infection." (PMID 31415618, 2019). "Interestingly, whole lung IL-11 content was maintained at relatively high concentrations in uninfected mice, and were elevated even further as a consequence of pneumonia." (PMID 31415618, 2019). "But to date, the role of localized IL-11 in acute pulmonary infections, such as pneumonia, is unknown." (PMID 31415618, 2019). "However, IL-11Rα mRNA levels were unchanged during pneumonia, suggesting that IL-11 signaling capacity is unlikely a function of receptor density." (PMID 31415618, 2019). "We next looked to see whether neutralization of IL-11 affected lung cellularity during pneumonia." (PMID 31415618, 2019). "Overall, these data suggest that while neutralization of IL-11 promotes lung injury during pneumonia, albeit relatively mildly (based on histological examination), baseline homeostatic levels of IL-11 do not appear to affect tissue integrity." (PMID 31415618, 2019). "Blockade of IL-11 with neutralizing antibodies resulted in a mild but significant decrease in neutrophil recruitment and increase in pulmonary edema during pneumonia, without detectable alterations in bacterial clearance." (PMID 31415618, 2019). "Neutralization of IL-11 did not alter BALF protein levels or neutrophil recruitment during S. pneumoniae pneumonia, with either a high (serotype 3) or low (serotype 19) virulence serotype." (PMID 31415618, 2019).